INS (insulin)
Diseases named in the same sentence as INS in open-access papers (continued):
Sharing a sentence is not in itself a finding about the gene and the disease.
type 1 diabetes (continued). "Evidence in rodent models suggests that myostatin expression is elevated in type 1 diabetes (Chen, Cao, Ye, & Zhu, 2009) and elevated myostatin expression is associated with impaired insulin signaling/sensitivity." (PMID 32652899, 2020). "Type 1 diabetes (T1D) patients suffer from continuous loss of pancreatic β-cell function and need life-long exogenous insulin treatment." (PMID 32151245, 2020). "Forty-seven per cent of participants progressing to insulin therapy within 3 years had type 1 diabetes and severe endogenous insulin deficiency, but this was often unrecognised." (PMID 30969375, 2019). "The effect of insulin degludec in limiting nocturnal hypoglycaemia remains undocumented in this high-risk type 1 diabetes population." (PMID 31337371, 2019). "Higher HbA1c levels were noted to be associated with higher rates of type 1 diabetes and insulin use, 2.5% glucose dialysate, a lower proportion of males, and higher hemoglobin and CRP levels." (PMID 30824808, 2019). "Type 1 diabetes is characterised by a deficiency of insulin caused by immunologically mediated damage to pancreatic beta cells, leading to raised blood glucose levels." (PMID 31164368, 2019). "Type 1 diabetes is an autoimmune disorder characterised by loss of insulin-producing beta cells of the pancreas." (PMID 31511930, 2019). "Type 1 diabetes (T1D) is an autoimmune disease caused by the T-cell mediated destruction of the pancreatic, insulin-producing beta cells." (PMID 31821343, 2019). "The disease is now predictable in humans with the measurement of type 1 diabetes associated autoantibodies (islet autoantibodies) in the peripheral blood which are directed against insulin and beta cell proteins." (PMID 30906293, 2019). "In Type 1 diabetes patients, estimated insulin sensitivity was associated with lower odds of developing diabetic retinopathy and proliferative diabetic retinopathy in a prospective, longitudinal, observational study." (PMID 31920963, 2019). "We generated a novel HLA-transgenic mouse model that expresses high-risk genes for type 1 diabetes (DRB1*03:01-DQA1*05:01-DQB1*02:01) as well as human CD80 under the rat insulin promoter and human CD4, on a C57BL/6 background." (PMID 31612266, 2019). "Type I diabetes mellitus (T1DM) is a severe disease characterized by a loss of insulin secretion from pancreatic β-cells." (PMID 31100973, 2019). "Often diagnosed in childhood, type 1 diabetes causes lifelong dependence on insulin, as well as an increased risk of cardiovascular disease, neuropathy, nephropathy, and other autoimmune and inflammatory conditions such as rheumatoid arthritis." (PMID 31295952, 2019). "Type 1 diabetes (T1D) is an autoimmune disease characterized by deficient insulin production in the body that tends to develop in childhood." (PMID 31094332, 2019). "Autoimmune destruction of insulin-producing pancreatic β cells, resulting in persistent hyperglycemia, underlies the pathogenesis of type 1 diabetes." (PMID 31686269, 2019). "Three studies in people with type 1 diabetes suggested that the risk of mild hypoglycemia is greater with low GI than with high GI foods when the usual carbohydrate-to-insulin ratio is used." (PMID 30871141, 2019). "Type 1 diabetes is characterized by loss of insulin-producing pancreatic β islets mainly as a result of autoimmunological aggression." (PMID 31757001, 2019). "The six patients with insulin‐triggered type 1 diabetes were all homozygous for the risk allele of CLEC16A rs12708716, and five patients were homozygous for the risk allele of CLEC16A rs2903692." (PMID 30970177, 2019). "Cow’s milk formula is associated with higher rates of type 1 diabetes and insulin autoantibodies in infants at genetic risk for developing type 1 diabetes." (PMID 30736445, 2019). "Type 1 diabetes is a chronic metabolic disease caused by an autoimmune reaction to pancreatic beta cells which excrete insulin." (PMID 30905141, 2019).
type 1 diabetes (continued). "Several studies have shown that overnight closed-loop insulin delivery can improve glucose control and reduce the risk of hypoglycemia in young patients with type 1 diabetes." (PMID 30849076, 2019). "The black bar indicates the risk variant having one or two risk alleles in each patient with insulin‐triggered type 1 diabetes." (PMID 30970177, 2019). "Type-1 diabetes is characterized by autoimmune-mediated pancreatic β-cell results in the deficiency of insulin, whereas type-2 diabetes is peripheral insulin resistance." (PMID 31645652, 2019). "We have developed, evaluated and validated clinical diagnostic models combining age at diagnosis, BMI, GADA, IA-2 and T1D GRS to provide estimates of a patient’s risk of having type 1 diabetes requiring rapid insulin therapy from diagnosis." (PMID 31558459, 2019). "Genotypic risk score for type 1 diabetes was inversely associated with detectable C-peptide secretion: the most strongly associated loci were the HLA and INS gene regions." (PMID 31438962, 2019). "For example, BACH2/rs3757247 is associated with childhood-onset type 1 diabetes and insulin-triggered type 1 diabetes in Japan." (PMID 32082072, 2019). "Do-it-yourself automated insulin delivery systems for people living with type 1 diabetes use commercially available continuous glucose sensors and insulin pumps linked by unregulated open source software." (PMID 31840095, 2019). "The early asymptomatic phase of type 1 diabetes is detected by the presence of autoantibodies against pancreatic β cell antigens such as insulin, glutamic acid decarboxylase (GAD), insulinoma-associated protein 2 (IA-2) and zinc transporter 8 (ZnT8)." (PMID 31286933, 2019). "Sensitivity analyses indicated a significant association between rotavirus vaccination and the use of insulin (HR = 0.71), hospitalization for type 1 diabetes (HR = 0.70), and for two or more type 1 diabetes codes with the use of insulin (HR = 0.70)." (PMID 31197227, 2019). "The objective of the present study was to assess the contribution of non‐human leukocyte antigen single‐nucleotide polymorphisms (SNPs) to the risk of developing insulin‐triggered type 1 diabetes." (PMID 30970177, 2019). "Although pathogenesis cannot be measured directly in humans, T-cell responses to (pro)insulin are strongly implicated in human type 1 diabetes." (PMID 31821343, 2019). "Intensive glucose management with insulin therapy for people with Type 1 diabetes reduces the risk of microvascular complications and cardiovascular disease." (PMID 31655586, 2019). "Type 1 diabetes is caused by the T cell mediated destruction of the insulin-producing β cells within the islets." (PMID 30766536, 2019). "Higher GA levels were noted to be associated with older age, type 1 diabetes, insulin use, 2.5% glucose dialysate, and higher CRP levels." (PMID 30824808, 2019). "Type 1 Diabetes (T1D) is an autoimmune disease that is associated with effector T cell (Teff) destruction of insulin-producing pancreatic beta-islet cells." (PMID 31695065, 2019). "The effect of the newer long-acting insulin degludec on risk of nocturnal hypoglycaemia remains undocumented in patients with type 1 diabetes and recurrent severe nocturnal hypoglycaemia." (PMID 31337371, 2019). "A common strategy prior to the prolonged PE in individuals with diabetes type 1 is to reduce the basal insulin doses by about 30–80% to reduce the risk of hypoglycemia." (PMID 31496994, 2019). "Type 1 diabetes is an organ-specific autoimmune disease characterised by immune-mediated beta cell destruction in pancreatic islets, which results in deficient insulin production." (PMID 31444529, 2019). "Type I diabetes (T1D) is a T cell-driven autoimmune disease that results in the killing of pancreatic β-cells and, consequently, loss of insulin production." (PMID 31156627, 2019).
type 1 diabetes (continued). "Type I diabetes (T1D) is an autoimmune disease caused by the selective destruction of insulin-producing pancreatic β-cells following infiltration of the islets of Langerhans by immune cells (insulitis)." (PMID 31507535, 2019). "Beyond this fact, individuals with type 1 diabetes often have a fear of hypoglycemia associated with PE, which often results in a reduction of the basal insulin dose before the start of the race." (PMID 31496994, 2019). "Type 1 diabetes (T1D) is characterized by the loss of insulin-producing cells and hence insulin secretion and metabolic control." (PMID 31757005, 2019). "Type 1 diabetes (T1D) is an autoimmune disease caused by targeted destruction of the insulin-producing beta cells through infiltration of autoreactive T lymphocytes." (PMID 31694869, 2019). "In combination with autoantibodies to several other islet antigens, including insulin, ZnT8A help predict risk of future type 1 diabetes." (PMID 31444530, 2019). "Regular physical activity (PA) offers many potential health benefits for individuals with type 1 diabetes (T1D) including improvements in insulin sensitivity and requirements, reduced risk of cardiovascular diseases and increased overall life expectancy." (PMID 30713524, 2018). "Type 1 diabetes (T1DM), also known as insulin-dependent or juvenile diabetes, is an autoimmune disease which causes destruction of the insulin-producing beta cells in the pancreas, preventing the body from adequately regulating blood glucose levels." (PMID 30166302, 2018). "The autoimmune destruction of insulin-producing β-cells in the pancreas causes type 1 diabetes mellitus (T1DM)." (PMID 30518745, 2018). "Type 1 diabetes is a T cell-mediated autoimmune disease characterised by the destruction of beta cells in the islets of Langerhans, resulting in deficient insulin production." (PMID 29594371, 2018). "Type 1 diabetes (T1D) is an autoimmune disease caused by the destruction of insulin-producing cells in the pancreas, by direct interactions with autoreactive pancreas infiltrating T lymphocytes (PILs)." (PMID 30050502, 2018). "Type 1 diabetes results from an absolute deficiency of insulin due to T cell-mediated autoimmune destruction of pancreas β cells." (PMID 30594258, 2018). "Type 1 diabetes (T1D) mellitus is a metabolic disease caused by loss of tolerance to self and consequent autoimmune destruction of insulin-producing pancreatic β-cells." (PMID 29491866, 2018). "Type 1 diabetes (T1D) is caused by the autoimmune destruction of the insulin-producing pancreatic beta cells." (PMID 29522531, 2018). "SSTR2 antagonism after recurrent hypoglycemia ameliorates the glucagon and corticosterone responses, as well as decreases the risk of insulin-induced hypoglycemia in rats with type 1 diabetes." (PMID 29342932, 2018). "Patients with type 1 diabetes are insulin deficient and therefore rely on chronic treatment with insulin (analogues)." (PMID 29486734, 2018). "Type 1 diabetes is characterized by absolute deficiency of insulin secretion, which necessitates daily (or continuous) external insulin injections to maintain carbohydrate metabolism and sustain life." (PMID 32232090, 2018). "Type 1 diabetes is an autoimmune disorder that causes destruction of β-cells and exogenous insulin is often required to treat the disease." (PMID 28916910, 2018). "Type 1 diabetes (T1D) is a chronic autoimmune disease caused by the selective destruction of the insulin-producing beta-cells in the pancreatic islets of Langerhans, resulting in insulin deficiency and hyperglycaemia." (PMID 30065302, 2018). "Type 1 diabetes is caused by the autoimmune destruction of pancreatic β-cells and a deficiency in insulin production." (PMID 30425651, 2018). "Standard insulin therapy in type 1 diabetes has been associated with increased complications including hypoglycemia, weight gain, and dyslipidemia." (PMID 29338714, 2018).
type 1 diabetes (continued). "Type 1 diabetes is caused by the immune system attacking and destroying the beta cells in the pancreas that produce insulin and commonly occurs in childhood with increasing incidence continuing in recent years." (PMID 30015622, 2018). "Insulin replacement is used to treat patients with type 1 diabetes, which is caused by the impairment of pancreatic beta cells producing insulin." (PMID 30384450, 2018). "The use of day-and-night hybrid closed-loop insulin delivery improves glycaemic control while reducing the risk of hypoglycaemia in adults, adolescents, and children with type 1 diabetes compared with conventional pump therapy or sensor-augmented pump therapy." (PMID 30292578, 2018). "One particular example is the VNTR region upstream of the INS promoter, as it was one of the very first loci to be associated with type 1 diabetes." (PMID 30060490, 2018). "Type 1 diabetes is characterized by the progressive loss of pancreatic beta cell function, eventually culminating in patients' dependence upon exogenous insulin to control blood glucose." (PMID 30356664, 2018). "Type 1 diabetes is characterized by the autoimmune destruction of pancreatic β-cells within the islets of Langerhans and loss of endogenous insulin production." (PMID 29342932, 2018). "Hybrid closed-loop insulin delivery improves glucose control while reducing the risk of hypoglycaemia across a wide age range in patients with suboptimally controlled type 1 diabetes." (PMID 30292578, 2018). "This, together with the impaired response to hypoglycaemia in type 1 diabetes, means that intensive insulin therapy is associated with increased glucose variability, weight gain and severe hypoglycaemia." (PMID 30132030, 2018). "Type 1 diabetes is an autoimmune disease in which cells of the body’s immune system cause destruction of insulin secreting β-cells in the pancreas, leading to a deficiency of insulin production." (PMID 30509933, 2018). "We estimated time‐to‐peak insulin action and insulin sensitivity in adults with type 1 diabetes during 12‐week closed‐loop insulin delivery and conventional insulin pump therapy, and demonstrated associations with clinical factors of interest." (PMID 28371223, 2017). "The rate of occurrence is higher in patients with Type 1 diabetes than in patients with Type 2, and use of insulin and high hemoglobin A1c are among the risk factors." (PMID 29375258, 2017). "Our study suggests that the shift towards fat oxidation occurs early in the course of type 1 diabetes and is affected by the loss of insulin action in the liver." (PMID 28192442, 2017). "Type 1 diabetes is a chronic disease caused by autoimmune destruction of the beta cells in the pancreas, leading to an absolute insulin deficit." (PMID 28620331, 2017). "Type 1 Diabetes (T1D) is an autoimmune disease with a genetic predisposition that primes the immune system, mainly T cells, to destroy the insulin-producing β cells of the pancreas." (PMID 29206239, 2017). "In type 1 diabetes, loss of insulin secretion leads to an imbalance in glucose metabolic pathways, and blood glucose is regulated by glycogen metabolism through the stimulation of glycogenesis and inhibition of glycolysis.." (PMID 28738076, 2017). "Type 1 diabetes is believed to be an autoimmune disease associated with irreversible loss of insulin secretory function that follows a chronic progressive course." (PMID 28835984, 2017). "Type 1 diabetes (TID) is characterized by a loss of pancreatic islet beta cell function resulting in loss of insulin production." (PMID 28380011, 2017). "Type 1 diabetes is mainly due to auto-immune-mediated pancreatic beta cell destruction, resulting in the deficiency of circulating insulin." (PMID 29285313, 2017). "Type 1 diabetes (T1D) is characterized by loss of pancreatic β cells whereas type 2 diabetes (T2D) is the consequence of decreased insulin response (resistance) which in later stages is accompanied by failure of pancreatic β cells." (PMID 28115020, 2017).
type 1 diabetes (continued). "Type 1 diabetes is characterized by the autoimmune destruction of the pancreatic islet β-cells with significant deficiency of the two glucose-modulating hormones, insulin and amylin." (PMID 29029531, 2017). "Analysis of pancreata obtained from patients with long-term type 1 diabetes (n = 3) showed nearly complete loss of insulin positive cells, while some DPP6 and glucagon positive cells remained." (PMID 29123178, 2017). "Deficiency of insulin/insulin like growth factor with anabolic activity on bone is associated with type 1 diabetes." (PMID 29240821, 2017). "The single most defining characteristic of Type 1 diabetes (T1D) is loss of pancreatic insulin-producing beta cells." (PMID 28055968, 2017). "An underlying hallmark of type 1 diabetes (T1DM) is the direct injury to the insulin-producing β-cells within the islets of Langerhans." (PMID 28694505, 2017). "Type 1 diabetes is a progressive autoimmune disease caused by the destruction of insulin secreting β-cells by T cells." (PMID 29035321, 2017). "Type 1 diabetes is characterized by the autoimmune destruction of the pancreatic beta cells, causing a deficiency of insulin." (PMID 28192442, 2017). "More studies using multiple infusions of the precursors to insulin-producing cells at different ages of NOD mice will help design protocols for clinical use of these cells in high-risk groups for type 1 diabetes." (PMID 28701182, 2017). "Type 1 diabetes is characterized by the autoimmune destruction and drastic loss of insulin-secreting pancreatic β cells leading to hyperglycemia." (PMID 28366620, 2017). "Type 1 diabetes is characterized by an absolute deficiency of insulin owing to the destruction of pancreatic beta cells, while type 2 is caused primarily by insulin resistance in peripheral target organs, such as the liver, muscle, and adipose tissue." (PMID 28251153, 2017). "Insulin deficiency has been considered the main cause of muscle atrophy in subjects with type 1 diabetes, as insulin treatment prevents muscle loss." (PMID 29273088, 2017). "The remaining ten donors with long-standing type 1 diabetes had almost solely insulin-deficient islets, but a few scattered insulin-positive cells were found in two cases." (PMID 27796420, 2017). "Type 1 diabetes (T1DM) is a progressive autoimmune disease caused by the destruction of insulin secreting β-cells by T cells." (PMID 29035321, 2017). "Type 1 diabetes is an autoimmune disease caused by T cell-mediated destruction of the insulin-producing β-cells in the pancreas." (PMID 28356069, 2017). "Conversely, there are also clinical situations (e.g., type I diabetes) in which mast cells and other inflammatory cells would exist chronically in an insulin-deficient milieu." (PMID 29430572, 2017). "Type 1 diabetes is classically described as a progressive disease with irreversible loss of insulin secretory function due to the destruction of beta cells." (PMID 28835984, 2017). "The majority of type 1 diabetes cases are attributed to a T cell-mediated autoimmune attack, which leads to loss of the insulin-producing beta cells of the islets of Langerhans in the pancreas." (PMID 28811863, 2017). "Those who are at risk of type 1 diabetes generally show islet cell antibodies, anti-insulin antibodies, antibodies against glutamic acid decarboxylase (GAD65), and antibodies against tyrosine phosphatases 1A-2 and 1A-2β." (PMID 28824543, 2017). "Early monitoring and modification of insulin sensitivity can also hamper diabetic nephropathy, one of the major causes of morbidity and mortality in type 1 diabetes." (PMID 28510587, 2017). "Type 1 diabetes is a disease that leads to the progressive loss of pancreatic beta cells and insulin production." (PMID 29075262, 2017). "Type 1 diabetes is characterised by insulin deficiency and hyperglycaemia due to extensive destruction of insulin-producing beta cells." (PMID 28526919, 2017).